FASN (fatty acid synthase)
Diseases named in the same sentence as FASN in open-access papers (continued):
Sharing a sentence is not in itself a finding about the gene and the disease.
breast cancer (continued). "Coherently, augmented fatty acid synthase (FASN) activity and cholesterol biosynthesis enhance the expression of EMT positive regulators and induce metastases in ovarian and breast cancer models." (PMID 32932943, 2020). "Six different human NPC cell lines, including HNE1, SUNE1, 5-F8, C-661, CNE1, and CNE2 along with a human breast cancer cell line control, SKBR-3, which is known to express high level of FASN15, were first assessed for FASN expression using WB analysis." (PMID 32944403, 2020). "We have shown previously in breast cancer cells cultured in high glucose that IGF-I reduced the interaction between BRCA1 and phosphorylated ACCA and that it induced cell growth in a FASN-dependent manner." (PMID 33212987, 2020). "FASN reportedly promotes EMT through TGF-β signaling in lung cancer and ErbB receptors in breast cancer." (PMID 32850862, 2020). "Currently, TVB-2640 is the only selective FASN inhibitor in clinical trials for the treatment of advanced solid tumors, including HER2+ advanced breast cancer, high-grade astrocytoma, colon cancer, and non-small cell lung carcinoma with mutations in KRAS." (PMID 32028963, 2020). "PRLR was among the top-100 genes positively correlated with FASN gene expression (r = 0.31, p < 0.0001) in the METABRIC breast cancer dataset." (PMID 33335078, 2020). "Under high glucose conditions, IGF-I induced a lipogenic phenotype by increasing FASN abundance downstream of ACCA and that ER-positive breast cancer cells were dependent on FASN upregulation for their proliferative response to IGF-I." (PMID 33212987, 2020). "In the context of EMT induction, the inhibition of fatty acid synthetic enzymes, including fatty acid synthase (FASN), 3-hydroxy-3-methylglutaryl-CoA reductase (HMGCR), and ACC, by miRNA has been reported to suppress EMT in breast cancer cell lines." (PMID 31027222, 2019). "Our results showed that 4-cholesten-3-one decreased the expression of ACC1, FASN and SCD1, indicating that 4-cholesten-3-one can reduce lipogenesis in breast cancer cells." (PMID 31477154, 2019). "BRCA1 siRNA 1 and siRNA 2 targeting different sequences of the BRCA1 gene, reduced ACCA phosphorylation and increased FASN abundance in both MCF7 and T47D breast cancer cells." (PMID 30323899, 2018). "In keeping with the increase of FASN during EMT, administration of the FASN inhibitor osthole to the MCF7 breast cancer cells abolishes cell scattering, EMT execution, migration, and invasion induced by the hepatocyte growth factor." (PMID 28352611, 2017). "Alpha-mangostin significantly inhibits intracellular fatty acid accumulation and induces apoptosis by suppressing intracellular fatty acid synthase (FAS) expression and activity in MCF-7 and MDA-MB-231 breast cancer cells." (PMID 28537893, 2017). "We conclude that DHA inhibits human breast cancer cell proliferation by inhibiting pAkt/Akt and pS6/S6 signaling and down regulating SREBP-1 and FASN expression." (PMID 29282029, 2017). "Next, we tested the level of FASN and ACC1, and the effect of clofibrate treatment on FASN and ACC1 in breast cancer cells." (PMID 26621841, 2016). "OPG interestingly pulled down lipid metabolic enzyme, fatty acid synthase (FASN), which is a key enzyme of the fatty acid biosynthetic pathway in breast cancer cells (unpublished results)." (PMID 27072583, 2016). "We also performed RT-PCR for profiling the gene expression of OPG, FASN, COX-2 and mPGES-1 in inflammatory breast cancer patient samples." (PMID 27270654, 2016). "Mass spectrometry analysis performed in this study revealed OPG interacts with fatty acid synthase (FASN), which is a key enzyme of the fatty acid biosynthetic pathway in breast cancer cells." (PMID 27270654, 2016). "Strong immunofluorescence staining for FASN and ACC1 was observed in the breast cancer cells compared to the control HMEC cells." (PMID 27270654, 2016).
breast cancer (continued). "High levels of FASN, OPG and COX-2/PGE2 expression in human breast cancer tissue sections and breast cancer cells suggested that there must be a loop among these tumorigenic factors." (PMID 27270654, 2016). "Since we observed higher protein levels of FASN and ACC1 in breast cancer cells, we stained SUM149PT, SUM1315MO2 and HMEC cells for FASN and ACC1, and analyzed by confocal microscopy." (PMID 26621841, 2016). "Since we observed abundant lipid bodies in breast cancer cells, as well as the overexpression of COX-2 and FASN, we wanted to decipher if FASN and COX-2 co-exist with the lipid bodies in breast cancer cells." (PMID 27270654, 2016). "Since breast cancer cells express high levels of OPG, FASN, and COX-2, we asked if the OPG rich microenvironment drives the transcription of COX-2 and FASN." (PMID 27270654, 2016). "Since SUM149PT and SUM1315MO2 cells have upregulated FASN and COX-2 pathways, we screened the effects of FASN inhibitor C75 and COX-2 inhibitor celecoxib or both in combination on the breast cancer cell lines using caspase 9 and caspase 3/7 assays." (PMID 27270654, 2016). "A novel positive feedback loop involving FASN/p-ERK1/2/5-LOX/LTB4/FASN sustains high growth of breast cancer cells (MCF-7 and LM-MCF-7; metastatic subclone of MCF-7 breast cancer cell line)." (PMID 27270654, 2016). "After establishing larger amounts of FASN and ACC1 in breast cancer cells, we decided to test the protein levels of these lipogenic enzymes in the presence or absence of clofibrate treatment." (PMID 26621841, 2016). "The role of pro-apoptotic hsa-miR-195 in inhibiting de novo lipogenesis via targeting genes overexpressed in breast cancer (BCL-2, FASN, ACACA, HMGCR, CYP27B1) makes hsa-miR-195 an effective anticancer molecule." (PMID 26632252, 2015). "Berberine regulated lipid metabolism under the inhibitions of AMPK, FASN, and TOFA in breast cancer cells MCF-7." (PMID 26351511, 2015). "We showed that the simultaneous blockade of FASN and HER2 pathways is effective in cells and in breast cancer models refractory to anti-HER2 therapies." (PMID 26107737, 2015). "In breast cancer cells medroxyprogesterone acetate (MPA) treatment for 6 days increased glucose uptake and fatty acid synthase (FASN) and activation of stearoyl-CoA desaturase-1 (SCD-1)." (PMID 25866757, 2015). "Together, these data show that the co-exposure of the FASN inhibitors, EGCG and G28UCM, with pertuzumab in parental and resistant HER2+ breast cancer cells is more active than either of the drugs used as a single agent." (PMID 26107737, 2015). "An altered lipid metabolism induced by berberine was observed under the inhibition of FASN, AMPK, and ACC in breast cancer cell MCF-7." (PMID 26351511, 2015). "We have developed new polyphenolic anti-FASN compounds that exhibit in vitro and in vivo anticancer activity improving the antitumor efficacy and the toxic effects of classical FASN inhibitors, in HER2+ breast cancer cells and mouse models." (PMID 26107737, 2015). "The expression of FASN was significantly higher in HER-2 type breast cancer, and lower in luminal A and TNBC type breast cancer (p<0.001)." (PMID 26334757, 2015). "Animal studies confirmed that the combination of the FASN and mTOR inhibitors inhibited the progression of ER+/HER2+ breast cancer xenografts." (PMID 24866893, 2014). "A FASN inhibitor and an mTOR inhibitor synergized to diminish the malignant phenotype of ER+/HER2+ breast cancer cells." (PMID 24866893, 2014). "We found that the mTOR inhibitor rapamycin inhibited the transcriptional activation of the FASN promoter and FASN mRNA expression in breast cancer cells, especially in ER+/HER2+ breast cancer cells." (PMID 24866893, 2014). "There is bidirectional crosstalk between FASN and HER2 in cancer cells.FASN overexpression positively correlates with HER2 amplificationin breast cancer cells." (PMID 24866893, 2014).
breast cancer (continued). "FASN was more highly expressed and had a more active promoter in ER/HER2-positive breast cancer cells than in breast cancer cells positive for only ER or HER2." (PMID 24866893, 2014). "The crosstalk between ER and HER2 activated mTOR through the PI3K/AKT pathway and then promoted the expression of FASN, contributing to malignant transformation in ER+/HER2+ breast cancer cells." (PMID 24866893, 2014). "Fatty acid synthase (FAS) has been proven over-expressed in human breast cancer cells and consequently, has been recognized as a target for breast cancer treatment." (PMID 24894151, 2014). "The inhibition of these signaling pathways down-regulated the transcriptional activity of the FASN promoter and FASN overexpression; this inhibition was more significant in ER/HER2-positive breast cancer cells." (PMID 24866893, 2014). "The overexpression of FASN in cancer cells has been reported to be regulated by a single oncogene, Akt, and HER-2 pathways through the hypoxic-inducible factor-1α (HIF-1α) in breast cancer cells." (PMID 25255125, 2014). "Cerulenin, a FASN inhibitor, synergized with rapamycin to induce apoptosis and inhibit cell migration and tumorigenesis in ER/HER2-positive breast cancer cells." (PMID 24866893, 2014). "PI3K activity was thought to be the mediator of the HER2 control on FASN expression because LY294002, a known PI3K inhibitor, abrogated HER2 induced FASN protein production in the HER2 overexpressing normal mammary epithelial and breast cancer cells." (PMID 23725225, 2013). "The FASN transcript was readily detectable in SKBR3 and HepG2 (a breast cancer cell line and a hepatocarcinoma cell line, respectively), which served as the positive controls." (PMID 22485149, 2012). "G28UCM inhibits fatty acid synthase (FASN) activity and the growth of breast carcinoma xenografts in vivo, and is active in cells with acquired resistance to anti-HER2 drugs, which make it a candidate for further pre-clinical development." (PMID 22177475, 2011). "BT474 human FASN+ and HER2+ breast carcinoma xenografts served as the tumour target for the in vivo studies." (PMID 22177475, 2011). "FASN phosphorylation was induced by heregulin in HER2-overexpressing SKBR3 and BT474 breast cancer cells." (PMID 21080941, 2010). "In this study, we further investigated the relationship between HER2-regulated FASN tyrosine phosphorylation and FASN activity, as well as the role of FASN in promoting cell invasion in HER2-overexpressing breast cancer cells." (PMID 21080941, 2010). "Our findings support the following model: cell invasion was regulated by the functional interaction between FASN and HER2 in HER2-overexpressing SKBR3 and BT474 breast cancer cells." (PMID 21080941, 2010). "Together, these results suggest the microRNAs-449/FASN axis as a potential therapeutic target in combination with anti-HER2 agents to overcome trastuzumab resistance and to improve treatment response in HER2-positive breast cancer patients." (PMID 40133809, 2025). "However, a more recently developed selective and reversible FASN inhibitor (TVB-2640) has shown promising results, including dose-dependent efficacy in advanced solid tumors like HER2-positive breast cancers and has advanced to Phase II clinical trials." (PMID 40055794, 2025). "FASN exhibits higher expression in breast cancer tissues than normal tissues, and inhibition of it affects breast cancer cell proliferation, metabolism, and migration capabilities." (PMID 40923764, 2025). "Lipid metabolism has been recognized as an important player in cancer cell specific biology, and a considerable number of studies have been devoted to the role of de novo FA synthesis by fatty acid synthase (FASN), an enzyme that is overexpressed in malignant breast tumors." (PMID 40759952, 2025).
breast cancer (continued). "In HER2-positive breast cancer patients who have developed resistance toanti-HER2 therapies like trastuzumab or lapatinib, FASN inhibitors have shown promise in effectively reversing resistance, potentially serving as a sensitization strategy for HER2-targeted therapies." (PMID 40303293, 2025). "Prior studies in hepatocellular and breast cancers show that IGF2BP3 (IMP3) binds the 3′ UTR of SREBP1c mRNA, stabilizing the transcript and enhancing SREBP1c nuclear accumulation and transactivation of lipogenic targets, including FASN." (PMID 41614778, 2025). "Considering that resveratrol was previously shown to inhibit purified chicken FASN with an IC50 of 11.1 μg/mL in vitro, we further explored whether resveratrol modulates FASN expression and intracellular activity in breast cancer cells." (PMID 40733158, 2025). "Additionally, TVB‐2640, another FASN inhibitor, is currently being evaluated in clinical trials for several solid cancers, including NSCLC, HER2+ advanced‐stage breast carcinoma, and high‐grade astrocytoma." (PMID 40956032, 2025). "The development of novel FASN inhibitors is underway, and preliminary clinical trial data on TVB-2640 demonstrate its potential to mitigate tumor response in patients with non-small cell lung cancer and breast cancer when used in combination with paclitaxel." (PMID 38994204, 2024). "Additionally, the Wnt/β-catenin signaling significantly regulates the process of de novo adipogenesis in breast cancer cells, characterized by a substantial upregulation of ACC, FASN, and SREBP1-c expression." (PMID 38994204, 2024). "Similarly, targeting enzymes involved in fatty acid synthesis, like fatty acid synthase (FASN), offers a potential avenue for sensitizing breast cancer cells to chemotherapy." (PMID 39287822, 2024). "FASN enhanced proliferation and metastasis of breast cancer cells by attenuating the activation of AMPK/mTOR pathway, thereby impacting the sensitivity of chemotherapy or radiotherapy for breast cancer." (PMID 38408962, 2024). "In addition, for the first time, exposure to AP was demonstrated to drastically reduce intracellular FASN protein expression and lipid droplet accumulation in EMT6 and MCF-7 breast cancer cells." (PMID 38939097, 2024). "Our results establish that FASN-derived TAG is necessary not only for the migration of MCF10CA1a cells, but also for their survival in detached conditions, two processes required for breast cancer metastasis." (PMID 39678343, 2024). "miR-195 targets de novo lipogenesis genes, a hallmark in cancer cells especially in aggressive tumors, and that are related to the production of cell membranes for rapid cell proliferation through action on overexpressed target genes in breast cancer such as BCL-2, FASN, ACACA, and HMGCR." (PMID 38813102, 2024). "Similar results were obtained by inhibiting or knocking down FASN in mouse embryonic fibroblasts (MEFs), MCF-7 human breast cancer cells, WI-26 human lung fibroblasts and U2OS human osteosarcoma cells, showing that this effect is not cell-type- or species-specific." (PMID 37563253, 2023). "The Web of Science, PubMed, Embase, and Cochrane Library databases were searched to identify studies that evaluated the relationship between FASN expression and overall survival (OS), relapse-free survival (RFS), and disease-free survival (DFS) of breast cancer patients." (PMID 37124526, 2023). "Furthermore, we found that the targeted inhibition of the up-regulated FASN and ACC was an effective approach to limit the growth, proliferation, and metastasis of breast cancer cells." (PMID 37120513, 2023). "However, FASN is often upregulated in CRC, breast cancer, liver cancer, bladder cancer, HCC, and ovarian cancers." (PMID 37190313, 2023). "Moreover, FASN acetylation enhances its interaction with TRIM21 in HCC, TRIM21 can ubiquitinate and decrease the expression of FASN in breast cancer, and GNPAT inhibits TRIM21-mediated FASN degradation and promotes lipid metabolism." (PMID 37190313, 2023).
breast cancer (continued). "Breast cancer patients who may benefit from therapy regimens using FASN inhibitors, which may have highly toxic effects on HER2-overexpress breast cancers, could be recognized by the overexpression of HER2 of the tumor." (PMID 37124526, 2023). "The apoptotic activity of EGCG in breast cancer cells was independent of FASN protein expression levels, although EGCG‐induced apoptosis was demonstrated by downstream proteins AKT and ERK1/2." (PMID 35243817, 2022). "Upregulation of human epidermal growth factor receptor 2 (HER2) in breast cancer cells enhances the expression of fatty acid synthesis genes such as ACC1 and FASN, which are suppressed by PI3K and mTOR inhibitors, indicating that PI3K/AKT/mTOR can regulate fatty acid synthesis." (PMID 35624775, 2022). "Increasing evidence also shows that dysregulated expression of fatty acid synthase (FASN), complicating the endogenous synthesis of fatty acids and the adjustment of ERα signaling, may contribute to breast cancer onset and progress." (PMID 35508982, 2022). "In addition, fatty acid synthase (FASN), normally elevated in HER2-overexpressing breast cancers, was decreased in concentration, which was attributed to kahweol’s modulation of sterol regulatory element-binding protein-1c (SREBP-1c) activity." (PMID 36364160, 2022). "Surprisingly, we observed a specific decrease in FASN protein expression upon SRPK2 knockdown only in the MDA-MB-231 breast cancer cells and not int the MCF-7 cells." (PMID 36096767, 2022). "By n contrast to the in vitro results, G28UCM, a synthetic FASN inhibitor, was found to induce apoptosis in breast carcinoma xenografts by decreasing FASN enzymatic activity but not total FASN levels." (PMID 35243817, 2022). "Moreover, fatty acid synthase (FAS) and ErbB2 have been shown to promote breast cancer cell migration." (PMID 34944904, 2021). "FASN inhibition, however, fails to sensitize breast cancer cells to MCL-1- and BCL-XL-selective inhibitors such as S63845 and A1331852." (PMID 34675185, 2021). "Remarkably, FASN inhibition has minimal effect on non-malignant cells, because FASN has a low or absent expression in normal tissues but is overexpressed and hyperactivated in many carcinomas such as breast cancer." (PMID 34948368, 2021). "In HER2 -positive SKBR3 human breast cancer cells, overexpression of HER2 could stimulate the expression of fatty acid synthase (FASN) through PI3K/AKT or MAPK pathways, leading to tumorigenesis." (PMID 34026649, 2021). "In fact, a high expression of FASN was associated with poor OS, RFS, DMFS, and PPS (P < 0.05) for breast cancer patients with HER2 negative." (PMID 34879004, 2021). "However, notably, the expression of the lipogenic enzymes FASN and ACC are down-regulated in circulating breast cancer cells, which exhibit enhanced mitochondrial respiration that fuels cancer cell motility." (PMID 34073989, 2021). "As a result, various FASN inhibitors were developed as anticancer drugs, but most of them failed in clinical trials with the exception of TVB-2640, which is currently undergoing phase 2 clinical trials in combination with other drugs for HER2+ breast cancer." (PMID 34948233, 2021). "Several studies have demonstrated that overexpression of FASN in human breast cancer is induced by SREBP1c but not SREBP1a." (PMID 34158007, 2021). "Among those genes are insulin receptors, fatty acid synthase, lipoprotein lipase, adiponectin, leptin, acetyl-CoA carboxylase beta, and fatty acid binding protein 4 (FABP4), the latter being a new player connecting obesity with breast cancer development." (PMID 33801973, 2021). "When breast carcinomas were categorized into basal-like, HER2-enriched, and ER+ (luminal) molecular subtypes, both HER2-enriched and ER+ subgroups had significantly augmented FASN protein expression compared to basal-like breast carcinomas." (PMID 33800852, 2021).